RAN (RAN, member RAS oncogene family)
Diseases named in the same sentence as RAN in open-access papers (continued):
Sharing a sentence is not in itself a finding about the gene and the disease.
Huntington disease (4 papers, 2020 to 2026). Huntington disease (HD) is a rare neurodegenerative disorder of the central nervous system characterized by unwanted choreatic movements, behavioral and psychiatric disturbances and dementia. "This long CAG repeat, similar to that of diseases such as SCA8 and Huntington’s disease where RAN proteins have already been detected, makes a SCA3/MJD an intriguing candidate for another potential instance of RAN translation." (PMID 35406787, 2022). "As with previously identified RAN translation-associated disorders, such as SCA8 and Huntington’s disease, SCA3/MJD is a CAG repeat-expansion disorder with a long repeat stretch." (PMID 35406787, 2022).
glioblastoma (3 papers, 2015 to 2020). The most malignant astrocytic tumor (WHO grade IV). "Based upon our results together with results from other research groups, we proposed a model illustrating the mode of action of RAN in glioblastoma." (PMID 30671385, 2018). "RAN and its partner KPNB1 regulate nuclear import of their cargos to promote glioblastoma cell survival and to induce drug resistance in patients." (PMID 30671385, 2018). "RAN, member RAS oncogene family (RAN) was expressed in glioblastoma at the highest level among all candidates based upon cDNA microarray data." (PMID 30671385, 2018). "The role of RAN and nuclear transport mediated by RAN has not yet been widely explored in glioblastoma." (PMID 30671385, 2018). "By querying the TCGA GBM data using The Human Protein Atlas and the Glioblastoma Bio Discovery Portal, we found that RAN levels did not correlate with patient survival (P = 0.909)." (PMID 30671385, 2018).
psoriasis (3 papers, 2014 to 2025). An autoimmune condition characterized by red, well-delineated plaques with silvery scales that are usually on the extensor surfaces and scalp. "Even with the large number of genes differentially expressed, only 3 canonical pathways reached significance of p<0.05 at 24 h p.i., including Role of IL-17A in Psoriasis (p = 0.0136), RAN Signalling (p = 0.0178) and Role of RIG1-like Receptors in Antiviral Innate Immunity (p = 0.0454; Tab." (PMID 24618842, 2014). "Several TFs/uDBPs additionally showed altered expression in blood from psoriasis patients (increased: JUNB, STAT3, DTL, CAT; decreased: CUX2, ZNF559, AVEN, RUVBL1, RAN)." (PMID 25883770, 2015).
renal cell carcinoma (3 papers, 2009 to 2023). "Our data suggest that in t(X;1)(p11;q21)-positive renal cell carcinomas a PRCCTFE3-mediated interference with RAN-dependent MAD2B activity may lead to loss of control over cell cycle progression and, hence, malignant growth." (PMID 19753112, 2009).
cervical cancer (2 papers, 2016 to 2021). A primary or metastatic malignant neoplasm involving the cervix. "RANBP2 expression up-regulated by YTHDF1 might enhance the activity of RAN GTPase activity and aggravate the progress of cervical cancer, which might need more investigations in further study." (PMID 33816306, 2021). "They identified that oxidative stress-related proteins, such as receptor of activated protein kinase C 1 (RACK1), ras-related nuclear protein (RAN) and peroxiredoxin 1 (PRDX1), were IgG-interacting proteins in HeLa cells (cervical cancer)." (PMID 28536629, 2016).
colon cancer (2 papers, 2015 to 2024). "Subgroup analysis demonstrated that the combined RAN rs14035 CT + TT genotype was associated with rectal cancer, but not colon cancer." (PMID 26147304, 2015). "Its overexpression of RAN is related to poor clinical outcomes in patients with CRC 33, and CDK1 has been identified as a potential indicator of tumor recurrence in stage II colon cancer." (PMID 38356712, 2024). "In a subgroup analysis targeting cancer type, the combined RAN rs14035 CT + TT genotype was associated with decreased risk of rectal cancer (AOR = 0.640; 95% CI, 0.430–0.954; P = 0.028), but not colon cancer." (PMID 26147304, 2015).
diabetes mellitus (2 papers, 2015 to 2019). A metabolic disorder characterized by abnormally high blood sugar levels due to diminished production of insulin or insulin resistance/desensitization. "Stratified analysis revealed the RAN rs14035 combined CT+TT genotype was associated with decreased CRC risk in male patients without diabetes mellitus (DM) and in patients with rectal cancer." (PMID 26147304, 2015). "Our study may provide a new clue of epidemiology about the importance of miRNA processing genes (RAN, XPO5, DICER1, and TARBP2) in type 2 diabetes mellitus and diabetic vascular complications." (PMID 31354628, 2019). "The effects of RAN, XPO5, DICER1, and TARBP2 SNPs on diabetes progression were further analyzed." (PMID 31354628, 2019).
glioma (2 papers, 2020 to 2024). A benign or malignant brain and spinal cord tumor that arises from glial cells (astrocytes, oligodendrocytes, ependymal cells). "This study aimed to evaluate the association between RAN and RANBP2 gene polymorphisms and glioma susceptibility in Chinese children." (PMID 39041645, 2024). "Other potential functional gene polymorphism loci of RAN and RANBP2 will need to be evaluated in the search for novel glioma biomarkers." (PMID 39041645, 2024). "The research herein assessed the associations of RAN and RANBP2 gene polymorphisms with glioma susceptibility among 439 Chinese children." (PMID 39041645, 2024). "Despite the potential significance of the relations between RAN and glioma, only a few studies have investigated this topic." (PMID 39041645, 2024). "To investigate the relations between RAN/RANBP2 gene polymorphisms and glioma risk, we conducted a multicenter clinical study." (PMID 39041645, 2024). "Therefore, it is now necessary to further explore other potential functional gene polymorphism loci of RAN and RANBP2 to find novel glioma biomarkers." (PMID 39041645, 2024). "RAN and RANBP2 gene polymorphisms with glioma susceptibility in Chinese children." (PMID 39041645, 2024). "The effects of RAN and RANBP2 gene polymorphisms on glioma susceptibility in Chinese children are currently unknown." (PMID 39041645, 2024). "Although our results did not support the association of the selected SNPs with glioma, the association of additional RAN and RANBP2 SNPs with glioma remains worthy of further investigation." (PMID 39041645, 2024). "Logistic regression model‐calculated odds ratio and 95% confidence interval were used to verify whether the gene polymorphisms (RAN rs56109543 C>T, rs7132224 A>G, rs14035 C>T, and RANBP2 rs2462788 C>T) influence glioma susceptibility." (PMID 39041645, 2024). "However, the associations of RAN and RANBP2 gene polymorphisms with glioma risk have not been examined." (PMID 39041645, 2024).
head and neck squamous cell carcinoma (2 papers, 2022 to 2023). A squamous cell carcinoma that arises from any of the following anatomic sites: lip and oral cavity, nasal cavity, paranasal sinuses, pharynx, larynx, and salivary glands. "RAN, a member of RAS oncogene family, could promote the proliferation and migration ability of head and neck squamous cell carcinoma cells." (PMID 35559035, 2022).
larynx cancer (2 papers, 2015 to 2023). A primary or metastatic malignant neoplasm involving the larynx. "In turn, the rs14035 RAN CT heterozygote and DGCR8 rs417309 GG genotype were significantly inversely associated with the presence of larynx cancer." (PMID 26688807, 2015). "This is the first report considering the association of the risk of larynx cancer and SNPs of the following polymorphisms: DROSHA (rs6877842), DGCR8 (rs3757, rs417309, and rs1640299), RAN (rs14035), XPO5 (rs11077), DICER1 (rs13078 and rs3742330), and TARBP2 (rs784567)." (PMID 26688807, 2015).
melanoma (2 papers, 2020). A malignant, usually aggressive tumor composed of atypical, neoplastic melanocytes. "Additionally, RAN upregulation was also found in melanoma cell models, compared to normal melanocytes and in metastatic melanoma, compared to primary melanoma samples and melanocytic nevi." (PMID 33072757, 2020).
myeloma (2 papers, 2010 to 2025). "The role of the transcription factor XPB1 and the nuclear protein RAN, a member of RAS family, in the myeloma pathogenesis remains to be defined." (PMID 20459741, 2010).
non-alcoholic fatty liver disease (2 papers, 2023 to 2024). "Here, the authors show hyodeoxycholic acid (HDCA) ameliorates nonalcoholic fatty liver disease by inhibiting the formation of RAN/CRM1/PPARα nuclear export heterotrimer, resulting in increased nuclear localization of PPARα and activated fatty acid oxidation." (PMID 37673856, 2023).
non-small cell lung carcinoma (2 papers, 2018 to 2022). A group of at least three distinct histological types of lung cancer, including non-small cell squamous cell carcinoma, adenocarcinoma, and large cell carcinoma. "Congruently, ectopic expression of RAN activates PI3K/AKT signaling and promotes the invasive potential of non-small cell lung cancer cells." (PMID 30671385, 2018).
ovarian tumor (2 papers, 2020). "Silencing of RAN inhibited cell growth, or/and induced apoptosis in colon, nasopharyngeal, renal breast, and ovarian tumours." (PMID 33053689, 2020). "Meanwhile, the results of immunohistochemistry confirmed that shRAN or shHSBP1 caused the down-regulation of Vimentin, N-cadherin, and promoted the expression of E-cadherin, indicating that the knockdown of RAN and HSBP1 inhibited the invasive ability of ovarian tumor in vivo." (PMID 32398961, 2020).
prostate carcinoma (2 papers, 2019 to 2021). A carcinoma that arises from epithelial cells of the prostate gland. "The lasso results also showed that five genes (AR, PDHA1, RAN, DPP4 and DAZAP1) were the powerful composed factors of prostate cancer risk prediction model." (PMID 33407865, 2021).
viral infection (2 papers, 2010 to 2021). "RAN is considered an essential factor for nuclear transportation of protein in animal cells and plays a role in animal immunity against virus infection." (PMID 33191557, 2021).
chronic myeloid leukemia (1 paper, 2013). "These genes belonged to cellular networks including cell cycle G1/S checkpoint regulators, RAN signaling, chronic myeloid leukemia signaling, molecular mechanisms of cancer, FXR/RXR activation and hepatic cholestasis." (PMID 24377043, 2013).
complication (1 paper, 2019). Any disease or disorder that occurs during the course of, or because of, another disease, treatment, or procedure. "In the association analysis between diabetic vascular complications and SNPs, we found that T2DM patients who carried TT+TC genotype of rs14035 in RAN gene had a 1.89-fold increased risk of developing macrovascular complications compared with those with the CC wild-type genotype." (PMID 31354628, 2019).
endometrial cancer (1 paper, 2016). Primary or metastatic malignant neoplasm involving the endometrium (mucous membrane that lines the endometrial cavity). "Pre-miRNAs are exported into the cytoplasm to generate mature miRNAs through XOP5 and it cofactor RAN, some heterozygous XPO5 variations were found in colon, gastric and endometrial cancer." (PMID 27957388, 2016).
esophageal adenocarcinoma (1 paper, 2016). A malignant tumor with glandular differentiation arising predominantly from Barrett mucosa in the lower third of the esophagus. "Genome-wide association studies (GWAS) involving associations between esophageal adenocarcinoma risk and RAN(rs14035 C>T) or XOP5(rs11077 A>G) were included in this meta-analysis." (PMID 27957388, 2016).
esophageal cancer (1 paper, 2015). A primary or metastatic malignant neoplasm involving the esophagus. "On the other hand, data showed an association between occurrence of recessive variant of investigated RAN polymorphism and esophageal cancer (p = 0.024)." (PMID 26688807, 2015).
fragile X-associated tremor/ataxia syndrome (1 paper, 2015). Fragile X-associated tremor/ataxia syndrome (FXTAS) is a rare neurodegenerative disorder characterized by adult-onset progressive intention tremor and gait ataxia. "Additionally, a CGG repeat in the 5′ UTR of the neurodegenerative disease fragile X-associated tremor/ataxia syndrome (FXTAS)-linked FMR1 also gives rise to RAN translation products." (PMID 25806046, 2015).
Hypertension (1 paper, 2019). The presence of chronic increased pressure in the systemic arterial system. "Another three-factor [RAN rs14035, hypertension (HP), and duration of T2DM (DOD)] interaction model was found for macrovascular complications of T2DM (OR = 41.60, 95%CI = 11.75–147.35, P < 0.001)." (PMID 31354628, 2019). "In addition, another best three-factor interaction model (RAN rs14035, with hypertension and more than 5 years of T2DM duration) was also identified to be related to the increased risk of macrovascular complications of T2DM." (PMID 31354628, 2019). "Additionally, our results also demonstrate two feasible interactions, DICER1 rs13078, BMI and TG in T2DM and RAN rs14035, hypertension and duration of T2DM in diabetic macrovascular complications." (PMID 31354628, 2019).
ischemic stroke (1 paper, 2022). A stroke disorder caused by obstruction of blood flow to the brain, due to thrombotic (local blood clot formation) or embolic (due to a blood clot or other material traveling from another site) event. "In ischemic stroke, miR-324-5p downregulation and subsequently RAN upregulation could prevent neuronal cell proliferation and glucose uptake and promote apoptosis." (PMID 36035118, 2022).
lung adenocarcinoma (1 paper, 2017). A carcinoma that arises from the lung and is characterized by the presence of malignant glandular epithelial cells. "In TCGA lung adenocarcinoma data sets there was a small, statistically significant increase in HURP, AURKA, TPX2 or RAN mRNA levels correlating with SMARCA4 mutations of all types." (PMID 28102363, 2017).
lymphoma (1 paper, 2024). A malignant (clonal) proliferation of B- lymphocytes or T- lymphocytes which involves the lymph nodes, bone marrow and/or extranodal sites. "Immunofluorescence analysis of DLBCL sections showed that every MECR + cell expressed CD20, and the same pattern was observed in RAN + cells or ARSK + cells, indicating the expression of these genes in lymphoma cells." (PMID 38254162, 2024).
Portal vein thrombosis (1 paper, 2016). Thrombosis of the portal vein and/or its tributaries, which include the splenic vein and the superior and inferior mesenteric veins. "Survival of patients with HCC was associated with TNM stage, Child-Pugh class, portal vein thrombosis, surgical resection, chemotherapy or radiotherapy, DICER rs3742330 GG genotype, and RAN rs14035 CT genotype." (PMID 27611467, 2016). "Furthermore, a stepwise Cox regression analysis indicated that the Dicer rs3742330 and RAN rs14035 genotypes, together with TNM stage, portal vein thrombosis, history of surgical resection, and history of chemotherapy or radiotherapy, are independent prognostic factors for survival." (PMID 27611467, 2016).
pulmonary fibrosis (1 paper, 2025). Chronic progressive interstitial lung disorder characterized by the replacement of the lung tissue by connective tissue, leading to progressive dyspnea, respiratory failure, or right heart failure. "Even when exposed to chronic hyperosmotic stress, WNK2− chondrocytes maintained lower expression of genes associated with OA, pulmonary fibrosis and pathogen-induced cytokine storm, while NOTCH, RAC, RAN and integrin signalling pathways were upregulated." (PMID 40592720, 2025).
rectal cancer (1 paper, 2015). A primary or metastatic malignant neoplasm that affects the rectum. "In addition, in a subgroup analysis targeting cancer type, we determined the combined RAN rs14035 CT + TT genotype was associated with decreased rectal cancer risk." (PMID 26147304, 2015). "However, we found the RAN rs14035 CT + TT genotype was associated with a lower CRC risk in male patients and in all patients with rectal cancer." (PMID 26147304, 2015).
serous carcinoma (1 paper, 2014). "Based on Kaplan-Meier analyses, RAN, cytoplasmic XPO7 and TPX2 were significantly associated with poor overall patient survival, and RAN and TPX2 were associated with lower disease free survival in patients with high-grade serous carcinoma." (PMID 24625450, 2014). "Interestingly, unlike with all other RAN network proteins investigated, staining for the mitotic RAN partner TPX2 was found exclusively within the nuclei of HG serous carcinomas (p<0.001)." (PMID 24625450, 2014).
serous ovarian carcinomas (1 paper, 2014). "We herein extend these in vitro studies showing that RAN associated nuclear export and mitotic spindle assembly correlate with clinical outcomes in serous ovarian carcinomas." (PMID 24625450, 2014). "Overall, our findings indicated that the RAN network, including both of RAN’s main functions (nucleo-cytoplasmic transport and mitosis), are deregulated in serous ovarian carcinomas affecting tumor progression and patient survival." (PMID 24625450, 2014).
spinocerebellar ataxia type 8 (1 paper, 2022). Spinocerebellar ataxia type 8 (SCA8) is a subtype of type I autosomal dominant cerebellar ataxia (ADCA type I) characterized by cerebellar ataxia and cognitive dysfunction in almost three quarters of patients and pyramidal and sensory signs in approximately a third of patients. "RAN translation was discovered by pioneering work in Spinocerebellar Ataxia Type 8 (SCA8) after the mutation of the ATG initiation codon in the CAG-repeat containing ATXN8 gene did not block the expression of the polyglutamine (polyQ) repeat in transfected cells." (PMID 35406787, 2022).
squamous cell carcinoma (1 paper, 2025). A carcinoma arising from squamous epithelial cells. "In squamous cell carcinoma, miR-483-3p sensitized cells to apoptosis by targeting anti-apoptotic genes such as API5, BIRC5, and RAN." (PMID 40537919, 2025).